IL6 (interleukin 6)
Diseases named in the same sentence as IL6 in open-access papers (continued):
Sharing a sentence is not in itself a finding about the gene and the disease.
Erythema (continued). "Fatigue symptoms, erythema, and cytokine levels (IL-1β, IL-2, IL6, IL-8, TNF-α, and MCP-1) were registered at baseline, during treatment, and after radiotherapy completion." (PMID 24800238, 2014). "We found that topically applied IPyr ameliorated dorsal skin erythema in the UVB-irradiated mice diminished transepithelial water loss and reduced the mRNA expression of IL-1β, IL-6, Cox-2, and Bax." (PMID 24810606, 2014). "Notably, in this study, Nutroxsun® significantly lowered IL-8, IL-6, and IL-1α levels down to baseline levels in UV-exposed keratinocytes, correlating with the observed reduction in erythema." (PMID 40362239, 2025). "Moreover, in vitro studies have shown that capsaicin exposure triggers TRPV1-mediated Ca2+ influx in keratinocytes, leading to the release of inflammatory cytokines such as IL-6, IL-8, and TNF-α, which are linked to erythema, capillary dilation, and pain." (PMID 40041491, 2025). "Future work should examine PI-MED erythema in relation to other markers of systemic inflammation (e.g., plasma IL-6), bearing in mind that previous work has found weak and inconsistent associations between inflammatory markers across different measurement methods." (PMID 36424456, 2022). "Moreover, the application of GL can effectively relieve UV radiation induced erythema and leathery skin, associated with the down-regulated expression of inflammatory cytokines (TNF-α, IL-6 and IL-10)." (PMID 33526759, 2021). "C. acnes inoculated subcutaneously into the back of the ears induce ear swelling, redness, and erythema, which are associated with the local and systemic production of TNF-α, IL-6, and IL-8 as well as the infiltration of CD45+Ly6G+ neutrophils and CD45+F4/80+ macrophages into the infected tissue." (PMID 34361921, 2021). "IL-6 is also a pro-inflammatory cytokine, correlates with the extent of erythema, is inversely related to mean arterial pressure, correlates strongly with the occurrence of hypotension, causes increased expression of FcεRI and increased intracellular histamine, and prevents mast cell apoptosis." (PMID 24586553, 2014). "Additionally, genetic predispositions influencing inflammation, such as variations in interleukin genes (e.g., IL‐6, IL‐1β), may affect the degree of erythema and scarring, leading to differing outcomes among patients receiving the same treatment." (PMID 40414816, 2025). "This is in agreement with previous studies showing that IL‐6 per se promotes human keratinocyte proliferation in vitro and that ectopic IL‐6 expression in rat skin via naked DNA transfection induces keratinocyte proliferation, as well as lymphocytic infiltration and erythema." (PMID 35785521, 2022). "The researchers observed that CO2 can decrease the production of IL-6 and TNFα in human keratinocytes and the 3D epidermis, thereby decreasing the formation of UVB-induced erythema in human skin." (PMID 39857811, 2025). "Histamine, interleukins (IL-1, IL-6, IL-8), calcitonin gene-related peptides (CGRP), and TNFα are elevated eventually resulting in solar erythema accompanied by increased sensitivity beyond the affected area, due to mediator diffusion." (PMID 35753587, 2022). "It was found that CO2 suppressed TNFα and IL-6 production in human keratinocytes and the 3D epidermis and attenuated UVB-induced erythema formation in human skin." (PMID 33431967, 2021). "This study demonstrated that H(H2O)m prevented UV-induced erythema and DNA damage in human skin and also inhibited UV-induced MMP-1, COX-2, IL-6 and IL-1β expressions significantly." (PMID 23637886, 2013). "At the same time, the inflammatory factors IL-6 and chemokine CCL5 were both detected, and it was noted that they were upregulated in both PPD induration and EC erythema compared to the control and that their levels were significantly higher in the PPD induration group than in the EC erythema group." (PMID 38068935, 2023).
Erythema (continued). "According to the results of this study, EEFR effectively prevented epidermal hyperplasia and hyperkeratosis in DNFB-treated mice by inhibiting the production of TNF-α, IFN-γ, IL-6, and MCP-1, and thus, ameliorated scaling, erythema, excoriation, and skin thickening." (PMID 37047066, 2023). "In addition, PPD induration was found to significantly increase the levels of the inflammatory factor IL-6 and the chemokine CCL5 compared to EC erythema." (PMID 38068935, 2023). "Moreover, the application of GL can effectively remiss UVB radiation induced skin erythema and leathery skin, via inhibiting the production of inflammatory cytokines such as TNF-α, IL-6, and IL-10." (PMID 33526759, 2021). "The results showed that PZH could alleviate the erythema and swelling of hind paws of CIA mice, improve the pathological conditions of joint and decrease the production of IL-1β, IL-6 and IL-17 in serum and joints." (PMID 32256686, 2020). "We observed that the topical application of EK100 ameliorated dorsal skin erythema and hyperplasia in the UVB-irradiated mice; moreover, the effect may occur by reducing the expression of MMP-1, IL-6, iNOS, and NF-κB." (PMID 27626393, 2016). "Genomic and in vitro studies on RSCE have shown a direct negative link between RSCE and the expression of IL-6 by macrophages, whereas our clinical data reported a significant improvement of erythema and hyperactive vasculature, even from the first treatment of RSCE with microneedling." (PMID 39233774, 2024). "Crucially, these injections did not induce noticeable erythema, inflammatory cell infiltration, or upregulation of pro-inflammatory cytokines such as IL-6 and IL-1β, indicating that inflammation is not the primary factor responsible for PEG2000 segments detachment from NVs." (PMID 38296939, 2024). "The inhibition of LL37 could be a mechanism how both drugs improve the clinical features of rosacea such as erythema, telangiectasia and inflammation, since in a mouse model a LL37 injection led to such clinical features possibly through the enhanced expression of IL1, IL6 and MMP9 in mast cells." (PMID 40410272, 2025). "Also, similar to UV-induced erythema, we found that UV-induced expression of MMP-1, COX-2, IL-6 and IL-1β mRNA were not significantly changed after 30 min or 1 hr treatments of H(H2O)m (data not shown)." (PMID 23637886, 2013).
gingivitis (57 papers, 2012 to 2026). A disorder involving inflammation of the gums; may affect surrounding and supporting structures of the teeth. "The elevated concentration of IL-6 in children with gingivitis in the current study likely mirrors the underlying pathophysiology of local inflammation." (PMID 36163488, 2022). "IL6 is a useful diagnostic indicator to determine the progression of the gingivitis to a periodontal disease." (PMID 29375198, 2017). "The proinflammatory cytokines IL-6 and IL-1β were prominently associated with gingivitis, suggesting that the levels of these cytokines could predict or confirm oral inflammation." (PMID 36163488, 2022). "Eight of these studies investigated gingivitis in comparison with gingival health, and the genetic variants investigated mainly included SNPs of cytokine genes, such as IL1, IL6 and IL10, as well as an MMP gene." (PMID 40197750, 2025). "In patients with gingivitis, visfatin and IL-6 levels were higher than in the control group (p = 0.000 for both)." (PMID 41280712, 2025). "They made an ointment cream and tested it on an animal model of gingivitis by looking at gene expression of NF-κB, IL-1β, IL-6, p38, and TNF-α." (PMID 38978754, 2024). "The expression of proinflammatory markers such as TNF-α, IL-6, IL-8, IL-17, and IL-1β has been reported to be detected in the gingival crevicular fluid after gingivitis and can also be detected in saliva." (PMID 36998066, 2023). "In patients with gingivitis, levels of IL-1β, IL-6, IL-7, IL-13, IL-17, IL-21 and MIP-3α in gingival crevicular fluid in the Sg group were lower in comparison with the Dg group." (PMID 33417619, 2021). "We explored levels of Th17/Treg-related cytokines, targeting TGF-β, IL-4, IL-6, IL-10 and IL-17, using ELISA, and found that all cytokines were significantly elevated in the gingivitis patients, relative to healthy controls." (PMID 34234776, 2021). "Contact with dental materials can, in fact, cause an inflammatory response with over-production of inflammatory markers such as IL6, IL-8, IL1β, IL-18, all of which play major roles gingivitis and periodontal destruction." (PMID 33211211, 2021). "Gingivitis is a pathologic response to microbial byproducts, leading to proinflammatory cytokines such as interleukin (IL)-1, IL-6, and IL-8, tumor necrosis factor (TNF), and the like, that leads to the destruction of the periodontium." (PMID 32064220, 2020). "The objective of this study is to evaluate the salivary concentrations of IL-1β, IL-6, IL-8, IL-10, TNFα and IL-12p70 of DS individuals and compare to cerebral palsy (CP) and normoactive patients (all with gingivitis)." (PMID 32509226, 2020). "Salivary cytokines may be more reflective of local inflammation in the oral cavity than systemic inflammation, as suggested by elevated salivary IL‐1β, IL‐6, and IL‐8 levels in the presence of gingivitis in otherwise healthy children and adolescents." (PMID 40547317, 2025). "Finally, gingivitis produced changes in saliva, with salivary levels of GM-CSF, IL-6, IL-7, IL-15, IP-10, KC-like, IL-10, IL-18, MCP1, TNFα being statistically significantly higher in the saliva of CG2 dogs compared to CG1." (PMID 38521919, 2024). "The levels of 1β, IL-6, IL-8, and IL-10 were significantly higher in those with gingivitis." (PMID 36163488, 2022). "Gingivitis is characterized by an inflammatory response; inflammatory molecules such as IL-6 and anti-inflammatory molecules such as IL-10 may be altered in saliva." (PMID 36547041, 2022). "The concentrations of IL-1β, IL-6, IL-8 and IL-10 were elevated in the presence of gingivitis." (PMID 36163488, 2022). "However, TGF-β mRNA as well as TGF-β, IL-4, IL-6, IL-10 in the periperial blood and SIgA in the saliva were higher in the gingivitis group." (PMID 34234776, 2021).
gingivitis (continued). "The high TGF-β levels, accompanied by IL-6 in peripheral blood lymphocytes, activated Th17 cells and caused elevated percentage of CD4+ IL-17A+ Th17 cells in the peripheral blood of gingivitis patients, thereby secreting corresponding inflammatory factor IL-17A." (PMID 34234776, 2021). "The hypothesis of the study was that individuals with DS present higher levels of IL-1β, IL-6, IL-8, IL-10, TNFα and the p70 subunit of interleukin-12 (IL-12p70) cytokines when compared to individuals with CP and normoactive, all with gingivitis." (PMID 32509226, 2020). "According to Dunn`s multiple comparison test, dogs with DM presented statistically higher GM-CSF, IL6, IL15, and MCP1 levels as compared with CG1 (healthy gingiva), and lower KC-like chemokine as compared with CG2 (gingivitis)." (PMID 38521919, 2024). "Serum/plasma IL-β, IL-6, and TNF-α have been suggested to be elevated in individuals with both PD/gingivitis and T2DM compared to the PD+ T2DM−, PD− T2DM+, or PD− T2DM− groups." (PMID 37893143, 2023). "In their study, levels of interleukin (IL)-1β, IL-6, MMP-8, and PGE2 from 40 periodontally healthy subjects and 40 subjects with gingivitis were measured." (PMID 33615769, 2021). "ELISA results revealed higher levels of IL-17A, IL-10, IL-6 and TGF-β in plasma of gingivitis patients relative to normal controls." (PMID 34234776, 2021). "IL-1β, IL-6, IL-7, IL-13, IL-17, IL-21 and MIP-3α in GCF of T2DM patients with gingivitis were significantly downregulated by statins treatment." (PMID 33417619, 2021). "In subjects with gingivitis, compared with the Cg group, levels of inflammatory factors IFN-γ, IL-4, IL-5, IL-6, IL-10 and IL-13 were significantly lower in saliva in the Dg group (p<0.05)." (PMID 33417619, 2021). "IL-6, CXCL8, andCCL2 secretions were significantly higher after exposure to commensal biofilmsthan after exposure to gingivitis or cariogenic biofilms." (PMID 28892653, 2018). "A significant dose-dependent increase in the secretion ofcytokines IL-6, CXCL8, CCL2, and CCL5 was found for gingiva equivalents exposedto commensal, gingivitis, and cariogenic microbiome." (PMID 28892653, 2018). "The present study is the first report that demonstrated elevated serum levels of CRP, IL-6 and MCP-1 in the course of experimental gingivitis." (PMID 23408963, 2013). "Only one study reported the effect of mechanical treatment on gingivitis control measures by cytokines levels, and the results showed that, although reduction of inflammatory process occurs, the levels of IL-1β, IL-6, and IL-8 remain high compared to subjects without CP." (PMID 33717115, 2021). "Finally, for IL-6, the authors found that in the gingivitis group, IL-6 was higher, but the results were not statistically significant." (PMID 24790719, 2014). "Following this upregulation in the early stage, Il6 and Tnfsf11 markedly increased in the PRT in IP, but Tnf and Il1b showed no apparent changes after the gingivitis phase." (PMID 38548743, 2024).
liver failure (57 papers, 2005 to 2025). A liver disease characterized by the liver losing or has lost all of its function. "In the high IL-6 group, the causes of death included 3 patients who died due to the progression of intrahepatic tumors and 3 patients who died from liver failure unrelated to tumor progression (both 10.7%)." (PMID 39652104, 2025). "Liver failure, hospital-acquired infection, mechanical ventilation, and IL-6 levels were independent factors associated with 28-day mortality." (PMID 39724169, 2024). "Regarding the studies, Il-6 is an independent risk factor for death after 28, 90, and 180 days in patients with liver failure." (PMID 39273468, 2024). "Moreover, IL-6 has recently been shown to be an independent risk factor for death after 28, 90, and 180 days in patients with liver failure." (PMID 39273468, 2024). "Similarly, in hepatic failure mice, suppression of the IL-6/STAT3 signaling pathway has been associated with a substantial alleviation in both liver injury and inflammatory responses, as well as a decrease in AST and ALT levels." (PMID 38139043, 2023). "Some animal studies have revealed that IL-6-deficient mice had liver failure and defective hepatocyte regeneration in which a single preoperative dose of IL-6 prevented liver damages through returning gene expression and hepatocyte proliferation to near normal." (PMID 33987145, 2021). "Additionally, in an IL-6-deficient mouse model, liver failure occurred after hepatectomy." (PMID 31952110, 2020). "This triggers a robust inflammatory cascade with the release of pro-inflammatory cytokines such as tumor necrosis factor (TNF-α) and interleukin-6 (IL-6), driving hepatocellular damage and liver failure." (PMID 41163775, 2025). "High IL-6 levels correlate with post-hepatectomy liver failure and prolonged recovery, seen in patients with extensive resections and complex adhesiolysis in our cohort." (PMID 41006707, 2025). "In contrast, in the low IL-6 group, 9 patients died due to tumor progression (32.1%), and 2 patients died from liver failure unrelated to tumor progression (7.1%), indicating a difference in the causes of death." (PMID 39652104, 2025). "Liver failure, hospital-acquired infection, mechanical ventilator use, and interleukin-6 ≥37 pg/mL were independent predictors of 28-day mortality." (PMID 39724169, 2024). "For instance, IL-6 is an indispensable element in liver regeneration, and IL-6 deletion impairs liver cell proliferation characterized by hepatic failure in IL-6-depleted mice." (PMID 36131263, 2022). "Previous studies have persistently reported the activation of microglia cells, increased inflammatory factor levels (e.g., TNF, IL-6, and IL-1β), Alzheimer's type II astrocytosis, and neuronal cell death in patients with liver failure." (PMID 32256557, 2020). "Clinical trials and animal experiments have showed that liver failure also significantly increased some inflammatory molecules including cytokines interleukin-1 (IL-1), interleukin-6 (IL-6), and tumor necrosis factor-alpha (TNF-α) in plasma." (PMID 30041501, 2018). "Our study revealed, that the level of IL-6 were increasing in parallel to the grade of liver failure classified according to the CTP and MELD score." (PMID 26107937, 2015). "Together, these data indicate that CCR2 and CCR4 signaling are required for microglia activation and subsequent production of the proinflammatory cytokines IL-1β and IL-6 following AOM-induced liver failure." (PMID 25012628, 2014). "A similar case with regard to dissociation between IL18 and CRP as well as IL6 was reported in which a patient was suffered from progressive liver failure requiring liver transplantation in the relapse of AOSD." (PMID 24455384, 2013). "Analyses of serum revealed elevation of proinflammatory cytokines (TNF alpha, IL-6), cytokines (IL-2R), anti-inflammatory cytokines (IL-4) and chemokines (IL-8) as well as signs of rhabdomyolysis and hepatic failure." (PMID 16285034, 2005).